TRAV38-1 (T cell receptor alpha variable 38-1)
Description:
V region of the variable domain of T cell receptor (TR) alpha chain that participates in the antigen recognition. Alpha-beta T cell receptors are antigen specific receptors which are essential to the immune response and are present on the cell surface of T lymphocytes. Recognize peptide-major histocompatibility (MH) (pMH) complexes that are displayed by antigen presenting cells (APC), a prerequisite for efficient T cell adaptive immunity against pathogens. Binding of alpha-beta TR to pMH complex initiates TR-CD3 clustering on the cell surface and intracellular activation of LCK that phosphorylates the ITAM motifs of CD3G, CD3D, CD3E and CD247 enabling the recruitment of ZAP70. In turn ZAP70 phosphorylates LAT, which recruits numerous signaling molecules to form the LAT signalosome. The LAT signalosome propagates signal branching to three major signaling pathways, the calcium, the mitogen-activated protein kinase (MAPK) kinase and the nuclear factor NF-kappa-B (NF-kB) pathways, leading to the mobilization of transcription factors that are critical for gene expression and essential for T cell growth and differentiation. The T cell repertoire is generated in the thymus, by V-(D)-J rearrangement. This repertoire is then shaped by intrathymic selection events to generate a peripheral T cell pool of self-MH restricted, non-autoaggressive T cells. Post-thymic interaction of alpha-beta TR with the pMH complexes shapes TR structural and functional avidity.
Synonyms: TRAV381; TCRAV14S2; TCRAV38S1
Gene: T-cell receptor variable (V) gene on chromosome 14 (22,271,968 to 22,272,563, forward strand). Ensembl gene ENSG00000211816.
Subcellular location: Cell membrane
Gene Ontology:
Biological process: immune response
Cellular component: immunoglobulin complex; plasma membrane
Homologues: Orthologues: chimpanzee TRAV38-1 (83% identical), macaque TRAV38-1 (79% identical), mouse Trdv2-2 (68% identical), tropical clawed frog trac (31% identical). Paralogues in human: TRAV38-2DV8 (87% identical), TRAV5 (34% identical), TRAV17 (33% identical), TRAV13-1 (32% identical), TRAV13-2 (31% identical), TRAV21 (31% identical), TRAV6 (29% identical), TRAV25 (28% identical), TRAV26-2 (28% identical), TRAV36DV7 (28% identical), TRAV20 (27% identical), TRAV27 (27% identical), and 10 more.
Diseases named in the same sentence as TRAV38-1 in open-access papers:
TRAV38-1 is named in the same sentence as 3 diseases in open-access papers, as found by Europe PMC text mining. Sharing a sentence is not in itself a finding about the gene and the disease. The quoted sentences say what the papers report.
COVID-19 (1 paper, 2024). A disease caused by infection with severe acute respiratory syndrome coronavirus 2. "The expression of genes such as TRDV2, TRVD1, TRAV38-1, TRBV3-1, TRAV13-1, and TRBV2 was among the 15 most decreased in all data of severe COVID-19." (PMID 38262689, 2024).
TRAV38-1 also shares sentences with these, for which no sentence is quoted: lung carcinoma (1 paper); squamous cell carcinoma (1).